GOLPH3 (golgi phosphoprotein 3)
Diseases named in the same sentence as GOLPH3 in open-access papers (continued):
Sharing a sentence is not in itself a finding about the gene and the disease.
cancer (continued). "Another example of how deregulated transport can promote cancer progression is the Golgi-localized phosphatidylinositol 4-phosphate effector protein GOLPH3, which is responsible for retrograde transport of glycosyltransferase, thereby controlling the lysosomal degradation of these enzymes." (PMID 37293129, 2023). "Finally, in vitro studies demonstrated that GOLPH3 regulates cell size, enhances growth factor-induced mTOR signaling in human cancer cells and modulates the response to rapamycin." (PMID 36387263, 2022). "GOLPH3 was found to act as an oncogene by promoting the Akt signalling in cancer cells." (PMID 35465326, 2022). "GOLPH3 is a validated oncogene amplified across various cancer types." (PMID 35465326, 2022). "Indeed, in the recent years, GOLPH3 has evolved as a drug target in cancers which develop resistance to conventional anti-cancer therapies." (PMID 35465326, 2022). "GOLPH3 appears to be an oncogene upregulated in many types of cancer, including CRC." (PMID 33670106, 2021). "To explore the mechanism by which GOLPH3 regulates the cancer stem cell-like phenotype and promotes metastasis in NSCLC, we used GSEA software programs to examine the relationship between the expression of GOLPH3 and the genes regulated by various signaling signatures." (PMID 34671013, 2021). "In the present study, we evaluated the roles of GOLPH3 in cancer metastasis and exosomes." (PMID 34671013, 2021). "First, we evaluated GOLPH3 expression in tumors and adjacent normal tissues through the TIMER database to confirm whether GOLPH3 mRNA expression level correlated with human cancers." (PMID 34497755, 2021). "Our evolutionary analyses suggest a more complex than anticipated evolutionary history of the GOLPH3 gene family, a scenario that could have implications for cancer." (PMID 34127736, 2021). "Furthermore, depletion of either GOLPH3 or MYO18A decreases cancer cell survival following DNA damage." (PMID 33670106, 2021). "GOLPH3 is over-expressed in many cancers and it is proposed that GOLPH3 might contribute to cellular transformation by affecting glycosylation of key cancer-relevant glyco-proteins." (PMID 34111527, 2021). "Moreover, they reported increased tumor growth when cancer cells overexpressing GOLPH3 were injected into the flasks of athymic nude mice." (PMID 32023813, 2020). "Remarkably, the study of Farber-Katz clearly showed that the DNA-PK/GOLPH3/MYO18A pathway is necessary for cell survival of cancer cells after DNA damage, indicating that Golgi fragmentation may contribute to tumor development and maintenance." (PMID 32023813, 2020). "In this context, GOLPH3 overexpression can promote cell survival upon DNA damage, which may be relevant to the cancer phenotype." (PMID 32433026, 2020). "This was consistent with the results obtained from other studies in several types of cancer, which demonstrated that GOLPH3 might play an oncogenic role in tumorigenesis." (PMID 33134174, 2020). "Furthermore, the SOX8 and GOLPH3 mRNA levels were obviously up‐regulated within TSCC tumor tissues relative to those within matched non‐cancer counterparts." (PMID 32307911, 2020). "In any case, in different types of cancer cells, the levels of GOLPH3 could affect the glycosylation of EGFR in different ways, and this could result also in different outcomes." (PMID 33238647, 2020). "However, the mechanistic basis that links the mTOR pathway to GOLPH3 remains to be elucidated, and multiple molecular mechanisms have been suggested to explain how GOLPH3 drives cancer." (PMID 32023813, 2020). "GOLPH3 is localized in the Golgi apparatus, widely involved in many important physiological processes, and plays an important role in glycosyltransferases location, glycosylation, and secretory trafficking which were related to cancer development." (PMID 32454851, 2020).
cancer (continued). "GOLPH3 has been considered an oncoprotein because its overexpression promotes increased cell proliferation, cell migration, and cell invasion in a variety of cancer cell lines." (PMID 33238647, 2020). "GOLPH3 also enhances cancer cell survival if the administered drug is a DNA damage-inducing chemical, thus its knockdown might be exploited in combination with these substances to enhance the efficacy of chemotherapy." (PMID 32023813, 2020). "Moreover our results suggested that the SOX8 level was increased within tumor tissue compared with that in para‐cancer normal counterpart, which showed positive correlation with the GOLPH3 level." (PMID 32307911, 2020). "Just like GOLPH3, MYO18A is a driver of human cancers, and several have papers indicated that defective Golgi-to-PM trafficking might contribute to GOLPH3-driven malignant secretory phenotypes." (PMID 32023813, 2020). "Seven studies 11, 16, 24, 26-29 with 856 NSCLC patients were eligible to evaluate the correlation between overexpression of GOLPH3 and OS of cancer patients, including seven studies 11, 16, 24, 26-29 for univariate analysis and four studies 11, 16, 26, 28 for multivariate analysis." (PMID 31737112, 2019). "Therefore, we performed a meta-analysis including all eligible studies to reveal the authentic value of GOLPH3 in cancer outcome and clinicopathological characteristics thereby providing more evidence for clinical practice." (PMID 31737112, 2019). "Given the genetic diversity in cancer, a still outstanding aspect is how in this inherent heterogeneity GOLPH3 could possibly exert its oncogenic function." (PMID 30779783, 2019). "Several studies have shown that GOLPH3 is related to the prognosis of cancer." (PMID 31921678, 2019). "Moreover, an increasing number of reports show a strong correlation between overexpression of GOLPH3 and poor cancer prognosis." (PMID 30779783, 2019). "Thus, to understand the different roles that the overexpression of GOLPH3 have in different cancer cells, we have also set to compare the effect of knocking down its expression." (PMID 30779783, 2019). "In this regard, we are investigating possible differences that could arise from GOLPH3 overexpression in different types of cancer cells." (PMID 30779783, 2019). "Therefore, our data add a new piece that has to be considered for a more complete understanding of the role that GOLPH3 plays in cancer." (PMID 30779783, 2019). "Therefore, our findings support the use of GOLPH3 expression levels as a clinical marker to predict responsiveness to DNA damaging cancer therapies of NB patients." (PMID 31557970, 2019). "GOLPH3 promotes growth factor-induced mTOR signaling in human cancer cells." (PMID 29996891, 2018). "Golgi related genes GOLPH3 has been reported to regulate many kinds of cancers proliferation." (PMID 29534690, 2018). "We also found the upregulation of GOLPH3 in ER positive (ER+) cancer tissues (n = 808)." (PMID 29534690, 2018). "In addition, GOLPH3 was found to be involved in the growth, differentiation and proliferation of cancer cells via mammalian target of rapamycin (mTOR) signaling." (PMID 28801637, 2017). "However, the molecular mechanism of GOLPH3 in cancer process, especially in migration and invasion, remains poorly understood." (PMID 28332316, 2017). "We found unexpected differences that support the notion that in different cancer cells, overexpression of GOLPH3 functions in diverse fashions, which may influence specific tumorigenic phenotypes." (PMID 27123979, 2016). "Moreover, increased GOLPH3-positive macrophages were related to low proliferative activity of cancer cells and characterized tumors localized on the trunk and extremities." (PMID 27706081, 2016). "Following studies revealed a number of mechanisms relating GOLPH3 to cancer progression." (PMID 27706081, 2016).
cancer (continued). "Interestingly, the oncogenicity of GOLPH3 seems to be mediated by a mechanism that involves enhanced signaling through the mammalian target of rapamycin (mTOR), conferring cancer cells hypersensitivity to rapamycin." (PMID 27123979, 2016). "In addition, the overexpression of GOLPH3 has been indicated to be correlated with clinically aggressive behavior of cancers and the prognosis of patients." (PMID 28983350, 2015). "In addition these researchers observe a 3-fold increase in tumor growth (relative to the vector alone control) when cancer cells overexpressing GOLPH3 are injected into the flanks of athymic nude mice." (PMID 25691054, 2015). "Therefore, our findings raise hope of using GOLPH3 expression levels as a clinical marker to predict responsiveness to DNA-damaging cancer therapies." (PMID 26500484, 2015). "Indeed GOLPH3 protein has been involved in several processes that, if altered, can contribute to cell transformation and cancer progression, including mitochondrial function, cell adhesion, cellular response to DNA damage and cytokinesis." (PMID 25691054, 2015). "Moreover, survival analysis showed that patients with high GOLPH3 expression have worse overall cancer-specific and progression-free survival than patients with low levels of GOLPH3." (PMID 26375441, 2015). "Based on these findings, we revealed that both GOLPH3 and YB-1 may be promising molecular targets for new therapeutic cancer strategies during the treatment of both androgen-dependent PC and castration-resistant PC." (PMID 28983350, 2015). "Moreover, scratch migration assays showed that GOLPH3 silencing significantly suppress the migration capability of both cancer cell lines." (PMID 26375441, 2015). "In addition, the resilience against DNA damage conferred by overexpression of GOLPH3 has particular relevance to cancer, as most standard cancer therapeutic regimens include DNA-damaging agents." (PMID 26500484, 2015). "Both GOLPH3 and YB-1 showed increased expression from benign to malignant tumors." (PMID 28983350, 2015). "Recent studies have suggested that GOLPH3 expression may correlate with the growth, proliferation and survival of cancer cells." (PMID 25104140, 2014). "Previous studies have demonstrated that GOLPH3 could regulate tumorigenicity by enhancing activation of mTOR signaling in human cancer cells, thereby influencing cell growth, cell size and proliferation." (PMID 25104140, 2014). "Golgi phosphoprotein 3 (GOLPH3) has been validated as a potent oncogene involved in the progression of many types of solid tumors, and its overexpression is associated with poor clinical outcome in many cancers." (PMID 24444035, 2014). "Interestingly, some studies have suggested that GOLPH3 regulates cancer cells by enhancing mammalian target of rapamycin (mTOR) activity." (PMID 25286393, 2014). "More recently, GOLPH3 has been identified as a novel oncogene in various cancer types." (PMID 25104140, 2014). "GOLPH3 expression levels or copy number status may therefore serve as a useful prognostic factor for cancer." (PMID 22905766, 2012). "The upregulation of GOLPH3 might also influence mTOR signaling through its effects on glycosylation, which influences the endocytosis and recycling of cancer-relevant glycoproteins that act upstream of the mTOR complex, leading to prolonged growth factor signaling." (PMID 40136688, 2025). "Moreover, in several types of cancer, GOLPH3 expression levels correlate with poor prognosis." (PMID 38391929, 2024). "Therefore, the exploration of this connection could provide a novel perspective on how environmental factors like BPA contribute to cancer pathogenesis through molecular mechanisms involving key regulatory proteins like GOLPH3." (PMID 38828452, 2024). "In addition, GOLPH3 (Golgi phosphoprotein 3) and CKAP4 (cytoskeleton-associated protein 4) are two proteins localized in the Golgi apparatus and upregulated in several types of cancer by enhancing the secretion of exosomal WNT3A." (PMID 37296620, 2023).
cancer (continued). "Interestingly, we confirmed our hypothesis and showed that GOLPH3 inhibited Akt phosphorylation at Ser473; this contradicts the majority of previous studies, which reported that GOLPH3 activates the Akt/mTOR signaling to accelerate cancer progression." (PMID 35190555, 2022). "Thus, we hypothesized that GOLPH3 participates in the regulation of exosomal protein secretion, leading to cancer progression." (PMID 34671013, 2021). "Thus, the role of the type of N-glycan branching on EGFR, as well as of GOLPH3 in this process, could be different in different cancer cell lines." (PMID 33238647, 2020). "Thus, a thorough analysis of GOLPH3 function and regulation in cytokinesis may open up new avenues to treat GOLPH3-overexpressing cancers." (PMID 32023813, 2020). "Based on these data, it has been suggested that GOLPH3 might affect the retromer-mediated recycling of the cell surface receptors including the receptor tyrosine kinases, leading to prolonged downstream signaling which influences cancer-relevant activities." (PMID 32023813, 2020). "Therefore, it is speculated that GOLPH3 plays an essential role in tumor initiation and progression in some types of cancer." (PMID 31737112, 2019). "Kaplan-Meier survival curves and log-rank test survival analyses showed that the overall survival, cancer-specific survival and progression-free survival of patients with low levels of GOLPH3 were significantly better than that for patients with high levels of GOLPH3 (all P < 0.05)." (PMID 26375441, 2015). "Given the known impacts of BPA on pathways similar to those influenced by GOLPH3, such as the PI3K/AKT pathway, a potential link between BPA exposure and GOLPH3 modulation in cancer warrants further investigation." (PMID 38828452, 2024). "The GOLPH3 complex and Golgi protein GM130 play an essential role in GOLPH3 glycosylation and membrane trafficking of cancer cells, with reduced expression leading to autophagy, decreased angiogenesis and tumorigenesis suppression when reduced." (PMID 37508488, 2023). "Overall, this review emphasizes the crucial significance of Golgi apparatus target proteins—specifically GOLPH3 and GOLGA proteins—in gastroenterological cancers." (PMID 37508488, 2023). "GOLPH3 and GOLGA proteins play a pivotal role in gastroenterological cancer, helping researchers unlock molecular mechanisms and identify therapeutic targets." (PMID 37508488, 2023). "Collectively, these data provided evidence that GOLPH3 interacts with CKAP4 to enhance the secretion of exosomal WNT3A, thereby inducing metastasis and the cancer stem cell-like phenotype in NSCLC." (PMID 34671013, 2021). "A role, or even an exclusive role, for GOLPH3 in retaining enzymes in the Golgi would certainly not be incompatible with these findings, as there is extensive evidence that changes in glycosylation are a hallmark of cancer cells, and they have been linked to increased tumor growth and invasiveness." (PMID 34473204, 2021). "In conclusion, our results indicate that GOLPH3 enhances the secretion of exosomes containing CKAP4 and WNT3A, which activate the WNT/β-catenin pathway, thereby contributing to metastasis and the cancer stem cell-like phenotype in NSCLC." (PMID 34671013, 2021). "Predictably, in vivo targeting of proteins inhibiting endocytosis such as GOLPH3 or the Na+/H+ exchanger NHE9 represent an attractive therapeutic strategy to limit EGFR oncogenic activity and to increase cancer cell responsiveness to TKI." (PMID 34831480, 2021). "The transcription level of GOLPH3 had a significant increase in LUAD patients based on gender, cancer stages, nodal metastasis status, and smoking habits." (PMID 34497755, 2021). "Taken together, our results indicated that GOLPH3 promotes the secretion of exosomal WNT3A to enhance metastasis and the cancer stem cell-like phenotype of NSCLC cells." (PMID 34671013, 2021).
cancer (continued). "The induction of DNA double strand breaks (DSBs) by chemotherapeutic drugs has been shown to activate a cytoplasmic DNA damage response, i.e. the GOLPH3/MYO18A/F-actin pathway, to promote Golgi apparatus dispersal and cancer cells survival." (PMID 32601379, 2020). "This is important in light of the attempts to assess the feasibility of using both the levels of GOLPH3 and the inhibition of EGFR glycosylation as tools to downregulate EGFR signaling and sensitize cancer cells to anticancer therapies." (PMID 33238647, 2020). "The phosphorylation of GOLPH3 results in augmented interaction between GOLPH3 and MYO18A, a novel putative cancer driver, well known to be involved in the Golgi pathway." (PMID 31557970, 2019). "Golgi phosphoprotein 3 (GOLPH3) is a new oncogene that is closely related to the tumor growth, metastasis in some types of cancer." (PMID 29534690, 2018). "Golgi phosphoprotein 3 (GOLPH3, also named GMx33 or GPP34) and its interacting proteins are hot topics in cancer research." (PMID 29285241, 2017). "We report for the first time the significance, contrary to that in cancer cells, of GOLPH2 and GOLPH3 expression in stromal TAMs and CAFs." (PMID 27706081, 2016). "The genes categorized into “cancer” group by IPA biofunctions analysis were GPX1, HDAC7, PSME2, MED6, GOLPH3 and MST4 (p<0.05)." (PMID 22438889, 2012). "Taking into account the role of GOLPH3 as a COPI adaptor with an essential role in Golgi glycosylation, it will be also important to investigate the landscape of the effects of GOLPH3 on glycome profiles in cancer cells." (PMID 40136688, 2025). "The enrichment of GOLPH3 within the TGF-β signaling pathway is particularly intriguing, as this pathway is well-established as a promoter of tumor growth and metastasis in various cancers." (PMID 38828452, 2024). "This review highlights two Golgi target proteins, GOLPH3 and GOLGA proteins, from this apparatus as they relate to gastroenterological cancers, and they were highlighted in the most works from the literature related to gastroenterological cancers." (PMID 37508488, 2023). "Despite the results suggesting a correlation between GOLPH3 and malignant tumor progression, to date, no studies have assessed the expression of GOLPH3 in lymph nodes." (PMID 37790749, 2023). "GOLPH3 exerts its effect by modulating key signaling pathways such as the PI3K/Akt/mTOR pathway which plays a vital role in cell survival, proliferation and migration—providing targetable precision medicine strategies against gastroenterological cancers." (PMID 37508488, 2023). "The GOLPH3-dependent oncogenic effect is then exerted by specific GSL species which most likely act on adhesion molecules, and Receptor Tyrosine Kinases (RTKs) promoting cancer growth and metastasis." (PMID 35465326, 2022). "Thus, investigating the functional dependence between GOLPH3 and FMRP will be also important in the light of a therapeutic strategy in human cancer." (PMID 34571985, 2021). "Thus, the PITPNC1/RAB1B/GOLPH3/MYO18A/F-actin module participates in anterograde traffic and in some cancers, allows malignant secretion to take place." (PMID 34111527, 2021). "Despite the vast amount of empirical evidence demonstrating the contribution of GOLPH3 to tumorigenesis and cancer, a full understanding of its molecular role has not yet emerged." (PMID 34127736, 2021). "In addition, GOLPH3 and STIP1 protein levels were dramatically upregulated in PDAC tissues compared with those in their matched para-cancer counterparts." (PMID 33134174, 2020). "In conclusion, our results demonstrate that the GOLPH3/AKT/mTOR axis is negatively regulated by miR-3135b resulting in apoptosis activation and a decreased proliferative capacity and cell cycle arresting of HCT-15 and SW-480 cancer cells." (PMID 32601379, 2020). "Notably, the subcellular localization of GOLPH3 and STIP1 was observed to be mainly in the cytoplasm of the cancer cells." (PMID 33134174, 2020).